NUP88 (nucleoporin 88)
Diseases named in the same sentence as NUP88 in open-access papers:
NUP88 is named in the same sentence as 31 diseases in open-access papers, as found by Europe PMC text mining. Sharing a sentence is not in itself a finding about the gene and the disease. The quoted sentences say what the papers report.
breast cancer (6 papers, 2010 to 2024). A primary or metastatic malignant neoplasm involving the breast. "The build-up of NUP88 has been linked to various types of cancer, such as breast cancer, colorectal cancer, and skin cancer." (PMID 39285301, 2024). "Some of them are Ribonucleic acid exports 1 (Rae1) linked to breast cancer pathophysiology and Nup88 which is overexpressed in ovarian cancer as well as in a broad spectrum of sarcomas, lymphomas and mesotheliomas." (PMID 23343205, 2013). "The same results were obtained when Nup88 was overexpressed in a breast cancer cell line MCF-7, which is epithelial-like well-differentiated cells (lanes 3 and 4)." (PMID 34331103, 2021). "Other members of the nucleoporin family have been linked with cancer including Tpr, NUP62, NUP214 and NUP358/RanBP2 with NUP88 and more recently, NUP43 specifically linked to poor outcome in breast cancer." (PMID 30935371, 2019). "The NPC, composed of NUP88, has been found to be strongly expressed in multiple tumor cells, including adenocarcinoma cells, cervical carcinoma cells, and breast cancer cells." (PMID 26490051, 2015). "Our findings of increased NPC staining in ovarian and mammary tumors substantiate this, and expression profiling confirmed an early observation that mRNA for Nup88 was over-expressed in a panel of ovarian carcinoma cell lines." (PMID 20174585, 2010).
ovarian carcinoma (4 papers, 2010 to 2018). A malignant neoplasm originating from the surface ovarian epithelium. "Nup88 is over expressed in ovarian cancer, lymphomas, mesotheliomas, a broad spectrum of sarcomas and in some epithelial cancers In breast, colorectal and hepatocellular carcinoma Nup88 over expression is associated with tumor aggressiveness." (PMID 24429466, 2014). "We first tested if known relevant nuclear envelope components in ovarian cancer were deregulated according to cancer nuclear morphological diversification, including LMNA, Lamin B1 and B2, Emerin, nucleoporins NUP88 and NUP1532." (PMID 30254278, 2018).
cervical carcinoma (3 papers, 2015 to 2025). A carcinoma arising from either the exocervical squamous epithelium or the endocervical glandular epithelium. "The aim of this study was to explore the direct association between Nup88 overexpression and malignant phenotypes in cervical cancer cells." (PMID 34331103, 2021). "Here, we investigated the effect of the overexpression of Nup88 on the migration and invasion of cervical cancer HeLa cells." (PMID 34331103, 2021). "In summary, we conclude that overexpression of Nup88 can stimulate migration and invasion activity of cervical cancer cells, contributing to the formation of malignant phenotypes." (PMID 34331103, 2021). "Taken together, these data indicated that Nup88 stimulates the migration of cervical cancer cells." (PMID 34331103, 2021). "Moreover, comparable Nup88-dependent migration was observed in another cervical cancer cell line, CaSki cells." (PMID 34331103, 2021). "NPC formation is closely associated with tumorogenesis and NUP107-160 members, particularly NUP88 and NUP107, have been shown to promote the survival and invasion of cervical cancer cells." (PMID 41153808, 2025). "Upregulation of MMP-12 protein by the overexpression of Nup88 was also observed in one other cervical cancer cell line and two prostate cancer cell lines but not 293 cells." (PMID 34331103, 2021).
head and neck cancer (2 papers, 2023 to 2024). A primary or metastatic malignant neoplasm affecting the head and neck. "We analyzed this co-upregulation of Nup88, and Nup62 in head and neck cancer tissue lysates, and observed that both Nup88 and Nup62 levels were higher in tumor tissues (n=4)." (PMID 36845732, 2023). "Here, we report that Nup88 and Nup62 mRNA and protein levels are elevated in head and neck cancer tissues." (PMID 36845732, 2023). "While a significant link of Nup88 overexpression in head and neck cancer exists but mechanistic details of Nup88 roles in tumorigenesis are sparse." (PMID 36845732, 2023). "Next, we analyzed the expression of Nup62 and Nup88 using the Oncomine database in the Ginos Head and neck cancer statistics." (PMID 36845732, 2023). "In conclusion, our data indicates that simultaneous overexpression of Nup62 and Nup88 in head and neck cancer stabilizes Nup88." (PMID 36845732, 2023). "Here, we report that Nup88 and Nup62 levels are significantly elevated in head and neck cancer patient samples and cell lines." (PMID 36845732, 2023). "Analysis of head and neck carcinoma MiPanda database revealed that Nup88 is particularly elevated in metastatic tumors when compared to benign tumors and cell lines." (PMID 36845732, 2023). "Moreover, limited information about the Nup88 and Nup62 expression level changes in various cancers including head and neck cancer impedes our understanding of the process." (PMID 36845732, 2023). "Since Nup88 and Nup62 form stable complexes and their expression levels show alterations in different cancers, we have probed how the expression and interactions of Nup88 and Nup62 correlate with head and neck cancers." (PMID 36845732, 2023). "For example, in head and neck cancer, NUP62 plays a role in stabilizing NUP88, which ultimately leads to the activation of the NF-κB pathway, promoting the proliferation of cancer cells." (PMID 38660294, 2024).
HIV-1 infection (2 papers, 2018). The type species of lentivirus and the etiologic agent of acquired immunodeficiency syndrome (AIDS). "Effects of NUP88 and NUP214 depletion on HIV-1 infection and MX2 activity were generally similar." (PMID 30084827, 2018). "Moreover, some Nup depletions (SEH1, NUP85, NUP160, SEC13, NUP98, NUP107, ELYS/ACHTF1, NUP93, NUP205, NUP88, and NUP214) that reduced both HIV-1 infection and MX2 activity in dividing HeLa cells, affected MX2 activity but not HIV-1 infection in non-dividing HeLa cells." (PMID 30084827, 2018).
leukemia (2 papers, 2010 to 2018). A malignant (clonal) hematologic disorder, involving hematopoietic stem cells and characterized by the presence of primitive or atypical myeloid or lymphoid cells in the bone marrow and the blood. "Nup88 interacts with the FG repeat nucleoporin CAN/Nup214, another nucleoporin and a proto-oncogene implicated in leukemia." (PMID 20497554, 2010). "Nup88 was reported to interact with the FG repeat nucleoporin CAN/Nup214, another nucleoporin and a proto-oncogene implicated in leukemia during interphase." (PMID 20497554, 2010). "It has been shown that some NUPs including NUP88, NUP98 and NUP214 make mechanistic contributions to carcinogenesis, particularly in leukemias." (PMID 29861858, 2018).
metastatic tumors (2 papers, 2023 to 2024). "The genes that were upregulated in the monosomy 3/metastatic tumors (PFKP, NUP88) exhibited an average fold change (FC) of 2.06 ± 0.82, whereas the downregulated genes (INSR, RBKS, and ZBTB20) differed by an average of −1.87 ± 0.44-fold." (PMID 38673877, 2024).
arthrogryposis (1 paper, 2024). A rare, non-progressive congenital disorder characterized by multiple joint contractures which are present at birth. "Mutation in the NUP88 gene (nucleoporin, 88 kilodaltons) leads to fetal akinesia deformation sequence 4 (FADS) which in addition to arthrogryposis, includes hydrops, polyhydramnios, and facial dysmorphism and leads to miscarriage or perinatal death." (PMID 39650934, 2024).
autoimmune disease (1 paper, 2022). A disorder resulting from loss of function or tissue destruction of an organ or multiple organs, arising from humoral or cellular immune responses of the individual to their own tissue constituents. "However, genetic variants or altered expression have not yet been implicated in autoimmune diseases, except for NUP88 in two GWAS of rheumatoid arthritis (RA)." (PMID 35632621, 2022).
cyst (1 paper, 2019). A sac-like closed membranous structure that may be empty or contain fluid or amorphous material. "Depletion of Nup62, Nup214 or Nup88 in cyst cells led to cell-autonomous defects in mRNA export in Drosophila." (PMID 31492028, 2019).
dysplasia (1 paper, 2021). A usually neoplastic transformation of the cell, associated with altered architectural tissue patterns. "Nup88 (88-kD Nup) has been found to be overexpressed in numerous malignant neoplasms, indicating that Nup88 may be a potential molecular marker of many malignancies and premalignant dysplasia." (PMID 34386417, 2021).
ischemic stroke (1 paper, 2025). A stroke disorder caused by obstruction of blood flow to the brain, due to thrombotic (local blood clot formation) or embolic (due to a blood clot or other material traveling from another site) event. "In ischemic stroke, we found that MPO, CALCRL, PPP5C, KTN1-AS1, CCR1, CTB-50L17.9, CCR9, ZNF362, ZIK1, ELP5, CKAP2, NUP88, and SEC16A show risk effects (OR > 1)." (PMID 40624693, 2025).
oral cancers (1 paper, 2023). "We find elevated Nup88 and Nup62 mRNA and protein levels in oral cancer tissues and a positive correlation between elevated Nup88 levels vis-a-vis poor survival rates." (PMID 36845732, 2023). "We also analyzed the co-expression of Nup62 and Nup88 in oral cancers in a collection of available datasets at MiPanda, and found that Nup62 and Nup88 transcript levels were significantly higher in primary tumors when compared to normal samples." (PMID 36845732, 2023). "We strengthened the observation made in cell line overexpression studies by analyzing p65 target genes in GEO & Oncomine oral cancer datasets already reported for Nup88 and Nup62 upregulation." (PMID 36845732, 2023). "Control gene (GAPDH) levels varied among patient samples, but the ratiometric analysis of Nup62 or Nup88 with GAPDH indicates that both Nups are significantly overexpressed in oral cancer tissues (n=4)." (PMID 36845732, 2023). "We report significantly enhanced levels of Nup88 and Nup62 protein in oral cancers." (PMID 36845732, 2023).
prostate carcinoma (1 paper, 2021). A carcinoma that arises from epithelial cells of the prostate gland. "However, we found that prostate cancer cell lines without integration of E6/E7 oncogenes also showed a Nup88-dependent increase in MMP-12 expression." (PMID 34331103, 2021). "Interestingly, increased expression of MMP-12 by Nup88 was also observed in CaSki cells and two prostate cancer cell lines (LNCap and PC-3 cells), but not in human embryonic kidney 293 cells." (PMID 34331103, 2021).
virus infection (1 paper, 2022). "Knockdown of Rae1, mTor, Nup88 or Nup214 did not restore VP2 expression under mutant CrPV(R146A) virus infection compared to wild-type infection, similar to that observed in the control dsRNA treated cells." (PMID 36455064, 2022).
cancer (13 papers, 2010 to 2025). A tumor composed of atypical neoplastic, often pleomorphic cells that invade other tissues. "Among the other highly DEGs in this cluster, Nup88, Dmxl1 and Igf2bp3 are associated with dysplasia and cancer, including CRC." (PMID 40890536, 2025). "Several independent lines of evidence indicate that elevated expression of Nup88 is linked with cancer." (PMID 34331103, 2021). "Given that upregulated MMPs are closely associated with invasion and metastasis of cancer cells, we decided to investigate whether malignant phenotypes induced by Nup88 are related to MMPs." (PMID 34331103, 2021). "Since Nup88 is overexpressed in many cancer patients, we hypothesized that the reason for Nup88-associated tumorigenesis may be related to disruption of Nup88-Nup214 interactions during interphase or mitosis." (PMID 20497554, 2010). "Consequently, it has been proposed that Nup88 might be used as a cancer prognostic and diagnostic marker." (PMID 29724197, 2018). "We asked if Nup88 and Nup62 can interact as reported in yeast to mediate the Nup88 overexpression dependent cancer phenotypes." (PMID 36845732, 2023). "Nup88, a constituent nucleoporin, is overexpressed in many cancers, and a positive correlation exists between progressive stages of cancer and Nup88 levels." (PMID 36845732, 2023). "Similar to NUP98, NUP88 is overexpressed in a variety of human cancers, and, in this state, it sequesters the NUP98-RAE1 complex in the cytoplasm away from APC/CDH1, disturbing mitotic checkpoint control and promoting aneuploidy." (PMID 36835439, 2023). "We propose that NF-κB pathway activation seems to be one of the mechanisms operating in Nup88 overexpressing cancer." (PMID 36845732, 2023). "The analysis revealed that Nup62 as well as Nup88 levels are upregulated in all different types of cancers analyzed, like the cancers of head and neck, breast, and stomach." (PMID 36845732, 2023). "While Nup88 is involved in nuclear export coordinated with Nup98 and Nup214, only Nup88 has been found to be highly expressed in a variety of cancer cell lines and tumors." (PMID 34331103, 2021). "In tumorigenesis, the incidental finding of Nup88 as a biomarker of cancer opened the door to detection of high levels of Nup88 in several types of tumors." (PMID 31137762, 2019). "Our results also suggest that Nup88 affects vimentin organization by altering its phosphorylation status, which contributes to cancer malignancy." (PMID 29724197, 2018). "Consistent with clinical observations, we found that overexpressed Nup88 enhanced multinucleated cell formation, leading to aneuploidy, enhanced genomic instability and tumorigenesis in cancer cell lines." (PMID 20497554, 2010). "Previous studies have demonstrated that elevated levels of NUP88 confer proliferation and migration advantages to cancer cells by sequestering NF-κB partly into the nucleus of unstimulated cells and consequently activating the NF-κB pathway at the level of nucleocytoplasmic transport." (PMID 39080077, 2024). "Together, our data indicate that when cancers overexpress Nup88, often Nup62 is co-expressed." (PMID 36845732, 2023). "Nup88 overexpression is becoming synonymous with cancer progression." (PMID 36845732, 2023). "Elevated expression of Nup88 has been reported for various types of malignant tumors." (PMID 34331103, 2021). "Elevated expression of the nucleoporin Nup88, a constituent of the nuclear pore complex, is seen in various types of malignant tumors, but whether this overexpression contributes to the malignant phenotype has yet to be determined." (PMID 34331103, 2021). "Indeed, overexpression of Nup88 appears to regulate the activity of NF-κB, a ubiquitous transcriptional factor involved in cancer progression, at the level of nucleocytoplasmic transport in tumor cells." (PMID 34331103, 2021). "Moreover, Nup88 levels exhibit a positive correlation with progressive stages of cancer." (PMID 36845732, 2023).
cancer (continued). "Thus co-overexpression of Nup62 in cancers may probably work through the stabilization of Nup88, and stable Nup88 can engage in proliferative activities inducing tumorigenic transformation." (PMID 36845732, 2023). "However, whether or how the upregulated expression of Nup88 contributes to cancer has yet to be fully established." (PMID 34331103, 2021). "However, the functional consequences of Nup88 overexpression in cancer remain unknown." (PMID 20497554, 2010). "Further, elevated Nup88 levels were found in several cancers irrespective of their type, degree of differentiation, or site of occurrence." (PMID 36845732, 2023). "Nonetheless, Nup214 is not co-overexpressed in Nup88 overexpressing cancers." (PMID 36845732, 2023). "While Nup88 protein levels were reported to be increasing with progressive stages of cancer, overexpression of no other nucleoporin could parallel these phenotypes." (PMID 36845732, 2023).
tumor (8 papers, 2010 to 2023). "Since Nup88 expression is linked to the progression of carcinogenesis, Nup88 has been proposed as a tumor marker." (PMID 20497554, 2010). "Nup88 expression is linked to the progression of carcinogenesis, Nup88 has been proposed as a tumor marker." (PMID 20497554, 2010). "Nucleoporin Nup88, a component of nuclear pore complexes, is known to be overexpressed in several types of tumor tissue." (PMID 29724197, 2018). "Because overexpressed Nup88 in tumor tissues is observed in the cytoplasm, we anticipated that Nup88 would colocalize with vimentin in the cytoplasm." (PMID 29724197, 2018). "Intriguingly, abnormally high levels of Nup88 has been detected in the cytoplasm of various tumor cells." (PMID 29724197, 2018). "In fact, it is reported that in tumor cell lines, Nup88, a component of NPC proteins, was strongly expressed, and its expression level correlated with malignancy." (PMID 23056526, 2012). "In the present study, we aimed to gain insight into the role of Nup88 during tumor malignancy." (PMID 34331103, 2021). "Furthermore, it has been reported that elevated Nup88 expression in tumor cells is correlated with tumor grade such as in colorectal cancer, breast cancer and hepatocellular carcinoma." (PMID 29724197, 2018). "Here, we have clearly demonstrated that alterations in the expression of the tumor marker Nup88 in vivo by modulating its concentration using RNAi and overexpression strategies enhanced multinucleated cells and multipolar spindle formation, leading to aneuploidy and enhanced genomic instability." (PMID 20497554, 2010).
infection (6 papers, 2018 to 2025). The state of being infected such as from the introduction of a foreign agent such as serum, vaccine, antigenic substance or organism. "Thus, altering nuclear pore composition via NUP88/214 depletion clearly modified the effect of MX2 on infection in a CA dependent manner, but had little effect on the action of CsA/CypA." (PMID 30084827, 2018). "In the case of HIV-1G89V, whose infection was inhibited by NUP88 and NUP214 depletion in HeLa cells, expression of MX2 completely restored infection." (PMID 30084827, 2018). "Notably, 9 nucleoporins (NUP58, NUP214, NUP98, NUP54, NUP62, NUP88, NUP153, POM121/NUP121 and RANBP2/NUP358) and the mRNA export factor Rae1 were present in both the CebN infection and transfection interactomes." (PMID 38712050, 2024). "While not required for HIV-1WT infection, NUP88/214 could play a direct role, as NUP88 bound to CA tubes and was depleted from cell lysates following incubation with CA tubes." (PMID 30084827, 2018).
NUP88 also shares sentences with these, for which no sentence is quoted: lymphoma (2 papers); mesothelioma (2); sarcoma (2); adenocarcinoma (1); Bardet-Biedl syndrome (1); benign tumors (1); colorectal cancer (1); cranioectodermal dysplasia 4 (1); hematological malignancies (1); hepatocellular carcinoma (1); hydrops (1); rheumatoid arthritis (1); skin cancer (1).